EGFR (epidermal growth factor receptor)
Diseases named in the same sentence as EGFR in open-access papers (continued):
Sharing a sentence is not in itself a finding about the gene and the disease.
colorectal cancer (continued). "Two studies have reported that an EGFR inhibitor in combination with cytostatic drugs achieved a better response rate for chemorefractory colorectal carcinomas than the cytostatic drugs alone." (PMID 21997136, 2011). "Aim of this study was to assess the role of EGFR-GCN in advanced colorectal cancer (CRC) patients receiving chemotherapy plus Cetuximab." (PMID 20398370, 2010). "Some, but not other studies, have shown an adverse prognostic effect for EGFR expression in colorectal cancer patients." (PMID 19997103, 2010). "Similar molecular events are being unearthed in colorectal cancers with respect to treatment outcomes with the anti-EGFR monoclonal antibodies cetuximab and panitumumab." (PMID 21274259, 2010). "The survival signature included the EGFR gene, a prominent gene contributing to prognosis variation in diverse solid tumor such as breast and colorectal cancer." (PMID 20421987, 2010). "A polymorphism in the EGFR gene (R497K) was associated with a marked decrease in EGFR phosphorylation and was reported to be a favourable prognostic marker in stage II/III colorectal cancers." (PMID 19997103, 2010). "Epidermal growth factor receptor (EGFR), evaluated by immunohistochemistry, has been shown to have prognostic significance in patients with colorectal cancer." (PMID 20842128, 2010). "Epidermal growth factor receptor (EGFR) has been validated as a therapeutic target in several human tumours, including colorectal cancer (CRC), non-small cell lung cancer (NSCLC) and squamous cell carcinoma of the head and neck (HNSCC)." (PMID 20459770, 2010). "The expression of EGFR was present in 71% of cases, which is similar to the rate of expression observed in colorectal cancer." (PMID 19935793, 2010). "The unique position of EGFR as a regulator of several key oncogenic pathways, together with the fact that EGFR is frequently expressed in colorectal cancer (CRC), has made it an excellent therapeutic target for the treatment of CRC patients." (PMID 20234366, 2010). "The validation of KRAS mutations as a negative marker of response to anti-epidermal growth factor receptor (EGFR) antibodies has meant a seminal advance towards treatment individualisation of colorectal cancer (CRC) patients." (PMID 20234366, 2010). "Cells of the colorectal cancer line HT-29 have a mutated BRAF gene (V600E) and are relatively resistant to cytotoxicity by anti-EGFR antibody cetuximab." (PMID 20976159, 2010). "Gene copy number (GCN) of EGFR and KRAS status predict response and outcome in patients treated with anti-EGFR therapy, but their prognostic significance in colorectal cancer patients is still unclear." (PMID 20842128, 2010). "Other oncogenic signalling pathways that are active in colorectal cancer include the epidermal growth factor receptor (EGFR), vascular endothelial growth factor receptor (VEGFR), and phosphatidylinositol 3-kinase (PI3K)/AKT pathways." (PMID 19935793, 2010). "EGFR is important in the survival of colorectal carcinoma cells and confers resistance to anoikis in suspension cultures of normal epidermal keratinocytes and mammary epithelial cells." (PMID 20074345, 2010). "Is it possible to further optimize efficacy by increasing dose of EGFR inhibitors in selected patients (i.e., treat to > grade 2 skin rash), which appears to be true for patients with colorectal cancer?" (PMID 19636422, 2009). "In the BOND study 329 EGFR expressing advanced colorectal cancer patients after one prior line of treatment were randomized to Cetuximab plus Irinotecan versus Cetuximab." (PMID 19584908, 2009). "Combining inhibition of VEGF (bevacizumab) and EGFR (cetuximab) signaling on a background of chemotherapy has been investigated in two recent colorectal cancer studies, which produced different outcomes." (PMID 19946413, 2009). "Monoclonal antibodies and small molecule inhibitors of EGFR are currently being evaluated in clinical trials of patients with lung and colorectal cancer." (PMID 19126225, 2009).
colorectal cancer (continued). "It would be interesting to know how many wild type K-ras colorectal cancers harbor B4GALT1 methylation as a mechanism of EGFR resistance." (PMID 19662090, 2009). "KRAS mutations are especially important predictors of unresponsiveness to EGFR-directed antibodies in colorectal cancers with EGFR gene amplification." (PMID 19636423, 2009). "In our series CISH EGFR GCN was also able to identify colorectal cancer patients more likely to respond to irinotecan-cetuximab therapy." (PMID 19712476, 2009). "It is known that non-small-cell-lung cancer (NSCLC) and colorectal cancer (CRC) patients with mutant KRAS show poor response to anti-EGFR therapy." (PMID 19358724, 2009). "Taken together data from all these studies suggest a strong role for EGFR GCN in predicting the activity of EGFR targeted monoclonal antibodies in colorectal cancer patients." (PMID 19712476, 2009). "Inhibition of the epidermal growth factor receptor (EGFR) signaling pathway represents a therapeutic option in advanced colorectal cancer." (PMID 19832985, 2009). "In this article, we will discuss targeted therapies for colorectal cancers (CRC) based on EGFR signaling pathway and review published data about the potential usefulness of KRAS as a biological marker for response to these therapies." (PMID 19386128, 2009). "FISH EGFR GCN has been previously demonstrated to correlate with clinical outcome of colorectal cancer treated with anti-EGFR monoclonal antibodies." (PMID 19712476, 2009). "This magnitude of anti tumor activity was seen with EGFR inhibitors in non small cell cancer and colorectal cancer and also with anti-HER2 therapy in patients with breast cancer." (PMID 19636422, 2009). "A more recent analysis investigating colorectal cancer patients receiving cetuximab showed once again that cases with high EGFR GCN have an increased likelihood to respond to therapy." (PMID 19712476, 2009). "Panitumumab and cetuximab are antibody-based drugs that inhibit EGFR, and are currently used in the treatment of colorectal cancer." (PMID 19545448, 2009). "The high level of EGFR response in colorectal cancer specimens has sparked great interest in using this target to develop more direct and specific therapies." (PMID 18059397, 2008). "The observation that forced expression of COX-2 in human colorectal cancer (CRC) cells stimulates proliferation through EGFR activation, suggests the likelihood of a cross talk between these two pathways." (PMID 19055708, 2008). "Cetuximab is an epidermal growth factor receptor (EGFR)-directed IgG1 chimeric monoclonal antibody showing antitumour activity in the treatment of advanced colorectal cancer." (PMID 18665167, 2008). "In this study we investigated a segment of the colorectal cancer pathway, involved in the signaling of the EGFR pathway, in an effort to discover molecular determinants of cetuximab response." (PMID 18700047, 2008). "Small-molecule inhibitors of EGFR have recently been tested in combination with chemotherapy in second-line treatment in colorectal cancer." (PMID 18059397, 2008). "Epidermal growth factor receptor (EGFR), which participates in signaling pathways that are deregulated in cancer cells, is a promising target in epithelial cancer, notably colorectal cancer." (PMID 18544172, 2008). "The EGFR inhibitor monoclonal antibodies panitumumab and cetuximab have significant activity in chemorefractory colorectal cancer, and cetuximab was shown to reverse clinical resistance to irinotecan." (PMID 18253119, 2008). "Asthenia has previously been reported with cetuximab (a chimeric anti-EGFR antibody) in colorectal cancer (CRC)." (PMID 19238629, 2008). "Cetuximab, a monoclonal antibody directed against the epidermal growth factor receptor, has activity against colorectal cancer." (PMID 18769609, 2008). "This contrasts with laboratory studies and also with clinical studies of EGFR inhibition using monoclonal antibodies in refractory colorectal cancer." (PMID 18253119, 2008).
colorectal cancer (continued). "The finding that Id-1 plays a role in the EGFR pathway, an alternative likely to be used in advanced colorectal cancers, indicates a new therapeutic target." (PMID 19014499, 2008). "The first approved mAb targeting EGFR as a single agent or in combination with irinotecan in patients with EGFR-expressing, metastatic and irinotecan-refractory colorectal carcinoma is the chimeric mAb cetuximab, which has shown favourable efficacy." (PMID 18319714, 2008). "As far as we know, this is the first study to show that Id-1 expression was significantly associated with EGFR and VEGF in colorectal carcinomas." (PMID 19014499, 2008). "The introduction of a novel class of targeted antineoplastic agents, such as those directed against the EGFR, have notably expanded the available therapeutic options for patients with advanced colorectal cancer." (PMID 17579627, 2007). "The epidermal growth factor receptor (EGFr) is considered a major target for treatment of colorectal cancer (CRC)." (PMID 17088913, 2006). "Other EGFR-targeted therapies such as the monoclonal antibody cetuximab (IMC-225) have shown antitumour activity in colorectal cancer, suggesting that targeting this pathway is valid." (PMID 16570047, 2006). "In this paper by Saltz and co-workers, 57 patients with EGFR-positive colorectal cancer that were refractory to both fluorouracil and irinotecan, were evaluated." (PMID 16508634, 2006). "Colorectal cancer (CRC) is considered a tumour showing EGFr overexpression, but EGFr expression ranges between 25 and 75%." (PMID 17088913, 2006). "Epidermal growth factor receptor (EGFR) is a transmembrane glycoprotein, which is reported to be overexpressed in approximately 70 to 75% of colorectal cancer." (PMID 17163999, 2006). "In the present phase II trial, we evaluated the efficacy and safety of the combination of cetuximab and irinotecan in EGFR-expressing colorectal cancer patients that progressed after oxaliplatin and irinotecan-based chemotherapies." (PMID 16508634, 2006). "We used the antibody manufactured by Zymed Laboratories in the current study, which was one of the three antibodies equally recommended by The Canadian Consensus Panel on EGFR Testing in Colorectal Cancer." (PMID 17163999, 2006). "In two previous studies of EGFR expression in colorectal carcinoma, the authors attempted reporting on the intensity of staining as weak, moderate and strong." (PMID 17163999, 2006). "A recent study in colorectal cancer patients revealed clinical efficacy of the EGFR inhibitory antibody cetuximab in patients with immunohistochemical EGFR-negative tumours." (PMID 15846297, 2005). "Activation of the EGFR pathway is particularly common in colorectal cancers and overexpression of EGFR correlates with more aggressive disease and poor prognosis." (PMID 16138927, 2005). "Both EGFR MAbs and TKIs that block activation of EGFR are now being used for the treatment of colorectal cancer." (PMID 16138927, 2005). "Inhibition of epidermal growth factor receptor (EGFR) signalling contributes to the therapy of colorectal cancer." (PMID 15870719, 2005). "The effect of ZD1839 (‘Iressa’), a specific inhibitor of the tyrosine kinase activity of the epidermal growth factor receptor, on the radiation response of human tumour cells (LoVo colorectal carcinoma) was evaluated in vitro and in vivo." (PMID 11953865, 2002). "A series of 24 paired samples of colorectal carcinoma and the respective normal colorectal mucosa were analysed for Epidermal Growth Factor Receptor (EGFR) content by means of a standardised ligand binding assay." (PMID 1739615, 1992). "Furthermore, cetuximab and panitumumab, two anti-epidermal growth factor receptor (EGFR) monoclonal antibodies frequently used in the treatment of colorectal cancer, directly affect kidney convoluted tubules, leading to renal magnesium wasting." (PMID 41601884, 2026).
colorectal cancer (continued). "Epidermal growth factor receptor inhibitors (EGFRIs) stand out as the most frequently used class of targeted agents and are widely used in the management of diverse malignancies, including lung, pancreatic, head and neck, and colorectal cancer." (PMID 41377804, 2025). "Furthermore, another study of FA (100–250 μg/mL) showed inhibition of proliferation in colorectal cancer cells (HCT 15) through downregulation of epidermal growth factor receptor (EGFR)." (PMID 40487371, 2025). "Additionally, in colorectal cancer, RNF43 mutations have been shown to predict response to combined anti-BRAF/EGFR therapies, further highlighting the therapeutic relevance of this alteration across tumor types." (PMID 40735046, 2025). "Survival rates have been reported to be higher in colorectal cancer patients treated with cetuximab who develop more severe AfR, suggesting that the severity of AfR may be indicative of the EGFR inhibitor's efficacy against cancer." (PMID 40503645, 2025). "Indeed, elevation of troponin has been observed in a prospective study of colorectal cancer patients with normal baseline troponin among 37% patients receiving the EGFR antibodies cetuximab or panitumumab." (PMID 41523436, 2025). "Additionally, the activation of STAT3 by nuclear PKM2 decreases the sensitivity of colorectal cancer cells to EGFR pathway tyrosine kinase inhibitors." (PMID 40057191, 2025). "RASGRP1 is a unique biomarker for colorectal cancer and is located in the EGFR pathway." (PMID 40861815, 2025). "Similarly, KRAS mutations in colorectal cancer (CRC) contribute to tumor development and are associated with poor prognosis and resistance to epidermal growth factor receptor (EGFR)-targeted therapies." (PMID 39786607, 2025). "Furthermore, the clinical trial that led to the approval of the EGFR-targeting ADC in nasopharyngeal carcinoma established its therapeutic utility in colorectal cancer." (PMID 41361128, 2025). "Mutations of ARID1A, an epigenetic regulator, in colorectal cancer patients were found to confer resistance to cetuximab rather than bevacizumab, with a relation to the EGFR/MAPK pathway." (PMID 40777019, 2025). "In addition, EGFR and RAS mutations are known to confer radioresistance in colorectal cancers, and some studies have investigated adding tyrosine kinase inhibitor or monoclonal antibody as a radiosensitizer." (PMID 40558246, 2025). "Additionally, incorporating EGFR inhibitors has emerged as a promising strategy to counteract resistance, particularly in colorectal cancer, where B-RAF inhibition alone leads to feedback activation of EGFR and MAPK signaling." (PMID 40141317, 2025). "Moreover, the dual targeting of B7-H3 and EGFR significantly restored chemotherapy sensitivity in colorectal cancer cells both in vitro and in vivo." (PMID 40004194, 2025). "In this study, PSP not only reduced the expression of EGFR but also promoted the death of colorectal cancer cells through the EGFR pathway in colorectal cancer cells, indicating that PSP has significant potential as a PD-L1 inhibitor and an immunological supplement in the treatment of CRC." (PMID 40507156, 2025). "For example, EGFR inhibitors like cetuximab have shown significant efficacy in colorectal cancer patients without KRAS mutations, extending progression-free survival." (PMID 41269529, 2025). "In targeted therapy, studies on KRAS G12C-mutated colorectal cancer have demonstrated significant efficacy of Sotorasib (AMG 510) as a monotherapy, while combining it with anti-EGFR agents like Panitumumab is being explored to address resistance and improve outcomes." (PMID 41361128, 2025). "Similarly, alterations in the EGFR/MAPK, Wnt/β-catenin, PI3K, TGF-β, Notch, and NF-κB pathways have been implicated in colorectal cancer [see review]." (PMID 40149916, 2025).
colorectal cancer (continued). "In RAS mutant colorectal cancer, liquid biopsy has enabled the identification of “neo-RAS-Wild-Type”, a transient phase characterized by the disappearance of RAS mutations, with significant clinical implications for re-sensitization to EGFR blockade." (PMID 40227564, 2025). "MiR-320d has been more extensively investigated in the gut, as it may inhibit the malignant phenotype of EGFR-positive colorectal cancer (CRC) and has been indicated as a putative blood biomarker for the early diagnosis of CRC." (PMID 40806453, 2025). "Moreover, P1 boosts T cell and IgA immune responses and concurrently inhibits colorectal cancer by disrupting the Reg IV/EGFR/Akt signaling pathway." (PMID 40002150, 2025). "The mechanisms underlying the enhanced radioresistance in KRAS-mutated tumours have been studied using colorectal cancer cell lines, which revealed that mutated KRAS isoforms activate EGFR and H-Ras, resulting in enhanced cellular radioresistance through PI3K/AKT signalling." (PMID 41226343, 2025). "Anti-epidermal growth factor receptor (anti-EGFR) antibodies are used to treat colorectal cancer." (PMID 40755575, 2025). "In contrast, IRE1α-XBP1s signaling was necessary for resistance to immunogenic cell death in colorectal cancer cells induced by combinatorial treatment of chemotherapy and cetuximab, a monoclonal antibody that blocks epidermal growth factor receptor (EGFR)-ligand interaction." (PMID 41372991, 2025). "One possible reason is that colorectal cancer tends to retain greater basal activation of EGFR." (PMID 40304209, 2025). "Colorectal cancers with V600E BRAF mutations may be treated with combinations of small molecule BRAF inhibitors and anti-EGFR monoclonal antibodies and the less common HER2 over-expressing colorectal cancers may be treated with drugs targeting this alteration." (PMID 40061138, 2025). "Saltz Saltz LB LB Phase II trial of cetuximab in patients with refractory colorectal cancer that expresses the epidermal growth factor receptor Phase II trial of cetuximab in patients with refractory colorectal cancer that expresses the epidermal growth factor receptor J. Clin." (PMID 40664764, 2025). "For example, patients with KRAS mutations are known not to respond well to EGFR (Epidermal Growth Factor Receptor) inhibitors, which are often used in colorectal cancer therapy." (PMID 40083375, 2025). "Background/Objectives: Colorectal cancer (CRC) remains a leading cause of cancer mortality globally, with KRAS mutations occurring in 30–40% of cases, contributing to poor prognosis and resistance to anti-EGFR therapy." (PMID 39941797, 2025). "The preclinical and clinical development of agents targeting epidermal growth factor receptor (EGFR) in colorectal cancer (CRC) were accompanied by big hype and hopes, though the clinical testing of such agents clashed with intrinsic and acquired resistance, greatly limiting their therapeutic value." (PMID 39470386, 2025). "Moreover, HPSE-induced SDC-1 shedding indirectly activates EGFR signaling, as soluble SDC-1 binds HB-EGF through intact HS chains, stimulating EGFR pathways and promoting chemotherapy resistance in colorectal cancer." (PMID 41301515, 2025). "KRAS mutations lie at the core of colorectal cancer (CRC) pathogenesis, driving persistent activation of the MAPK/ERK and PI3K/AKT pathways and conferring resistance to numerous therapies, particularly anti-EGFR antibodies." (PMID 39941797, 2025). "Interestingly, hub genes exhibited significant enrichment in pathways “Proteoglycans in cancer”, “HIF-1 signaling pathway”, “EGFR tyrosine kinase inhibitor resistance” and “Colorectal cancer”." (PMID 39968177, 2025). "FMRP facilitates colorectal cancer progression by stabilizing the mRNA of EGFR, a process that relies on m6A modification, suggesting that targeted intervention at specific m6A sites could serve as a therapeutic strategy." (PMID 40271197, 2025).